CD276 (CD276 molecule)
Diseases named in the same sentence as CD276 in open-access papers (continued):
Sharing a sentence is not in itself a finding about the gene and the disease.
tumor (continued). "In GC tissues with high expression levels of B7-H3 (CD276), the density of CD8+ T cells within the tumor was reduced, suggesting that B7-H3 may be involved in the mechanism of tumor evasion of immune responses." (PMID 36341377, 2022). "TNFSF9, CD276, CD40, CD274, and CD44 expression was downregulated in cluster 6 (hypoxic tumor)." (PMID 36685583, 2022). "Lastly, enoblituzumab, a humanized, Fc-engineered mAb binding CD276 has recently been investigated both as single-agent as well as in combination with pembrolizumab in a phase 1 trial in HNSCC, resulting in sustained inhibition of tumor growth." (PMID 36268020, 2022). "B7-H3 (CD276) is a tumor antigen that is overexpressed in various human malignancies and tumor-associated vasculature, but not in healthy tissues." (PMID 36341333, 2022). "In former studies, CD276 CAR-T cells showed potent antitumor activity against solid tumor cells; a dual-compartment targeted CD276 ADC antibody reagent could simultaneously destroy both tumor cells and tumor vasculature." (PMID 34344378, 2021). "According to correlation studies, patients with high CD276 expression are reported to have lower tumor infiltrating lymphocytes, without giving any insight about the underlying mechanism." (PMID 34290311, 2021). "Three major soluble factors were affected in the absence of CD276 on tumor cells: Dickkopf-related protein 1 (DKK-1), PAI-1, urokinase-type plasminogen activator receptor (uPAR)." (PMID 34290311, 2021). "A small sample of tumor culture medium was supplemented with soluble CXCL12 at a concentration of 100 nM to enhance immune cell migration and some CD276-CAR NK-92 cells were pre-treated with prostaglandin E2 (PGE2) at a concentration of 5.7 μM in order to block migration." (PMID 33925968, 2021). "The result showed that NXA1 expression was positively correlated with CD274 and CD276 expression, which indicated ANXA1 could influenced the tumor microenvironment by regulating these tumor immune genes." (PMID 34422796, 2021). "Furthermore, we divided the tumor sites into two groups according to COL1A1 expression and found that CD276 levels were positively correlated with the level of COL1A1." (PMID 33850663, 2021). "CD276 is a member of the B7 family, with structural similarities to PD-L1 that harbors a dual immunoregulatory role: either co-stimulating APC-induced T-cell activation, or acting as a co-inhibitor of T-cells, contributing therefore to tumor immune evasion." (PMID 33918733, 2021). "In order to assess COL1A1 correlation with CD276, we analyzed COL1A1 and CD276 expression in tumor sites and the adjacent non-tumor samples." (PMID 33850663, 2021). "Furthermore, we divided the tumor sites into two groups according to FN1 expression and found that CD276 levels were positively correlated with the level of FN1(P < 0.05)." (PMID 35141255, 2021). "In vivo, CD276 knockout decreases the expression of MYC and inhibits tumor growth." (PMID 33842369, 2021). "Though promising CD276 is as a potential gene target in anti-tumor therapy, the negative effects of CD276 regulation should be considered before the clinical transformation." (PMID 33842369, 2021). "We found that FN1 and CD276 showed significantly higher expression in tumor sites than in the adjacent no-tumor samples (P < 0.05)." (PMID 35141255, 2021). "The expression of IGF-1R is positively correlated with the expression of CD276 in most cancer types, and since CD276 is related to immunosuppression, this may explain why the increased expression of IGF-1R in tumor has an impact on the prognosis." (PMID 34804946, 2021). "CD276 expression was selectively reduced on macrophages upon αCD276 antibody treatment, while tumor cells were not affected." (PMID 34290311, 2021). "The results demonstrated that higher expression of CD276 in tumor cells, but not membrane localization or vascular expression, was significantly correlated with RFS (P < 0.001)." (PMID 31998416, 2020).
tumor (continued). "Moreover, the immune checkpoints B7-H3/CD276 and OX40 were found to be significantly co-expressed with core EMT genes, TGFB1, CXCR4, IL10, and IL6 on tumor microenvironment as vascular endothelial and myeloid cells." (PMID 32708431, 2020). "Differential expression of CD276 in tumor cells was scored as 0 (negative), 1 (weak), 2 (moderate), and 3 (strong)." (PMID 31998416, 2020). "CD276 was already reported overexpressed during pathological but not physiological angiogenesis, as well as in tumor endothelial cells and in neoplastic cells 118, and positively correlated with microvessel density." (PMID 31528221, 2019). "Overexpression of PlGF, CD109, CD137, and CD276 have been identified in ECs of tumor tissues in comparison to ECs of non-tumor tissues." (PMID 31555593, 2019). "The most interesting finding was that CD276 was expressed on both newly formed and pre-existing vessels inside the tumours but not in normal vessels outside the malignant lesion and not during physiological angiogenesis." (PMID 35582580, 2019). "Although most receptors/proteins that are increased in the tumor endothelium are also up-regulated in physiologic angiogenic processes, CD276 is not increased in the vessels of wounds or the corpus luteum." (PMID 21385454, 2011). "KCNN4 has been shown to have positive correlations with several costimulatory molecules (CD276, CD40, CD70, CD80, CD86), immune signaling receptors (IL2RA, MICB, NT5E), and multiple TNFRSF family members, suggesting its involvement in immune modulation, inflammation, and tumor‐immune interactions." (PMID 40952239, 2025). "CD276 is highly expressed in tumor tissues with expression in normal tissues being minimal." (PMID 39367484, 2024). "At the same time, activated CD8+ T cells mediated the CD16+ NK cell activation and secreted more IFN-γ to execute the killing function, whereas CD16+ NK cells could not achieve the cytotoxicity of CD276+ tumor cells when the CD8+ T cells were inactive." (PMID 39076970, 2024). "We found that in HNSCC, FAP expression is significantly correlated with CTLA4, HAVCR2, and CD276, suggesting that FAP may play a key role in regulating immune evasion and tumor immune suppression, but further exploration is needed to elucidate the specific mechanisms." (PMID 38826849, 2024). "However, CD276+ tumor cells were reduced significantly in the post-NICT group, while they still appeared in the post-NCT group, which means that CD16+ NK cells can recognize and kill CD276+ tumor cells after immune checkpoint blocker (ICB) treatment." (PMID 39076970, 2024). "It indicated that CD16+ NK cells that infiltrated tumor lesions could recognize CD276+ tumor cells but with no capability of cytotoxicity before the treatment of PD-1 inhibitors, while it can kill CD276+ tumor cells after the treatment of PD-1 inhibitors." (PMID 39076970, 2024). "In patients with ccRCC, a negative correlation was noted between tumor CD276 expression and PFI." (PMID 39210603, 2024). "Overexpression of ALYREF and YBX1 was accompanied by the upregulation of immune checkpoint inhibitors (such as CD276 and PDCD1) and downregulation of immune checkpoint stimulants (such as CX3L1, ITGB2, CD40LG and SELP), which promoted evasion of immune surveillance by these tumor cells." (PMID 38238581, 2024). "No CD276 immunoreactive cells were observed in the tissues outside the tumor." (PMID 37373167, 2023). "However, CD276 (B7-H3) and FoXO1 expression seem not to be directly involved in the acquisition and/or maintenance of tumor stem cell characteristics in vitro." (PMID 36901916, 2023). "Thus, a number of tumor cells and CTCs (CD87+, CD87+CD117+, and CD276+CD117+ and Axl+SOX2+, EGF+SOX2+, and CD87+SOX2+) may be interesting as diagnostic markers of SCLC or indicators of dynamic disease control." (PMID 36142766, 2022).
tumor (continued). "Of note, our results have distinguished that B7-H3, also known as CD276, might be a promising therapeutic target for CAR-based therapy, and there is evidence that it carries no risk of on-target off-tumor toxicity." (PMID 35432345, 2022). "Furthermore, GPC2 and CD276 expression levels were independent of the tumor’s MYCN amplification status." (PMID 35852863, 2022). "Similarly, in TCGA whole primary tumor samples proteomics data (n = 105), mir-29c positively correlated with AR and negatively correlated with CD276/B7H3, indicating that AR may upregulate mir-29c and subsequently downregulate its target CD276/B7H3." (PMID 36550153, 2022). "In the absence of CD276 on tumor cells, significantly lower macrophage infiltration was observed." (PMID 34290311, 2021). "The checkpoint molecule B7-H3 (CD276) is statistically increased in MGMT methylated tumour cores compared with unmethylated tumour cores of GBMs (p = 0.023); MGMT methylated tumour core counts: 14.07 [1.02] compared to MGMT unmethylated GBM (tumour core: 12.35 [0.87])." (PMID 33995529, 2021). "To investigate whether increased PAI-1 and as a result reduced uPA is the mechanism behind the reduced macrophage recruitment in the absence of CD276 on tumor cells, we added exogenous uPA to the spheroid-macrophage coculture." (PMID 34290311, 2021). "Tumour ECs are able to selectively upregulate inhibitory receptors of T cell activation including programmed cell death protein ligand 1 (PD-L1), programmed cell death protein ligand 2 (PD-L2), T-cell immunoglobulin mucin-3 (TIM3), and B7-H3 (also known as CD276)." (PMID 33917287, 2021). "Previously, we have shown that CD276-CAR NK-92 cells showed no undesirable off-target effects since CAR-mediated cytotoxicity only occurred in the presence of CD276 surface expression on target tumor cells." (PMID 33925968, 2021). "A significant decrease in tumor cell viability could be shown within two hours upon addition of CD276-CAR NK-92 cells and no tumor regrowth was detectable over a longer period of time." (PMID 33925968, 2021). "Therefore, we concluded that lack of CD276 expression on tumor cells has no significant impact on HCT116 cell spheroid formation." (PMID 34290311, 2021). "ACC patients were divided into subgroups according to their differential CD276 expression patterns (strong/moderate vs. weak/negative intensity in tumor cells; positive vs. negative tumor cell membranous location; positive vs. negative expression in tumor vasculature)." (PMID 31998416, 2020). "Anti-angiogenic therapy targeting VEGF, CD276, or endothelin B receptor has been shown to normalize tumor vasculature and could be used in combination with targeted therapy like CAR T cells to increase tumor infiltration." (PMID 30804938, 2019). "Notably, CD276 was expressed on both newly formed and pre-existing vessels present inside tumours but not in normal vessels outside the neoplastic mass and not during physiological angiogenesis (e.g., regenerating liver tissue)." (PMID 35582580, 2019). "Nevertheless, CD276 is not completely specific for the tumor endothelium because its expression may be induced by cytokines on the cell surfaces of B cells, T cells, and dendritic cells." (PMID 21385454, 2011). "Importantly, SPC25 showed a significant positive correlation with COAD expressing many immune checkpoint genes, especially NRP1, CD276, TNFSF14, and other important immunotherapeutic targets, which may also be closely related to the immune escape mechanism of ACC tumor cells." (PMID 38605119, 2024). "The results obtained showed that CD276 could positively regulate GBM cell proliferation, invasion, migration, angiogenesis, epithelial-mesenchymal transition (EMT), apoptosis and inflammation, whereas it negatively regulated GBM cell DNA damage and repair, cell cycle and tumor cell stemness." (PMID 36717836, 2023).
tumor (continued). "We found that CD276 and VEGFA expression was significantly positively correlated with the expression of OTUD6B in nearly all types of cancer, so were the immune checkpoint inhibitor genes HMGB1 and TLR4, suggesting that OTUD6B may provide some help for tumor immunotherapy through these targets." (PMID 36052059, 2022). "In addition to these cytokines, coculturing with tumor spheroids (inside and outside of the spheroids) or exposing to tumor-conditioned medium (generated from tumor spheroids) for 7 days, and cell adhesion to the culture plate in the absence of GM-CSF or M-CSF also induced CD276 upregulation." (PMID 34290311, 2021). "In a mouse model, an antibody-drug conjugate pyrrobenzodiazepine-conjugated CD276, eradicated both large established tumours and metastases and improved long-term overall survival potentially as a result of targeting both angiogenic and non-angiogenic tumour blood vessels." (PMID 35582580, 2019). "The CC tumor tissue and PSO exhibited negative expression of MSLN and MUC1 in the parenchymal region and positive expression of CD276." (PMID 38162496, 2023). "A significant correlation between tumor markers ALDH1-A1, -A2, and -A3, CD24, CD44 on one hand, and CD276, on the other hand, was not computed." (PMID 35563359, 2022). "In order to assess FN1 correlation with CD276, we analyzed FN1 and CD276 expression in tumor sites and the adjacent no-tumor samples." (PMID 35141255, 2021). "By multivariate Cox regression survival analyses, CD276 and TIM-3 double-positive group shows poor prognosis regardless of tumor stage and tumor grade." (PMID 35052695, 2021). "Of interest, the ratio of CD276+Plvap+ TEC relative to total TEC levels, rather than their absolute numbers, together with low levels of TAM and CAF play an important role in promoting tumor cell-specific NP delivery." (PMID 36494816, 2022). "As expected, single antigen–specific CAR T cells could not suppress tumor growth, although the GPC2 single CAR performed slightly better than did the CD276 single CAR because of the low expression levels of GPC2 in the CD276-overexpressing NALM6 cells." (PMID 35852863, 2022). "In the absence of CD276 on tumor cells, plasminogen activator inhibitor-1 (PAI-1) and urokinase plasminogen activator (uPA)—two recognized players in ECM remodeling—are affected, indicating that CD276 could be an upstream regulator for PAI-1 in tumor." (PMID 34290311, 2021).
cancer (661 papers, 2009 to 2026). A tumor composed of atypical neoplastic, often pleomorphic cells that invade other tissues. "Results indicated a significant positive correlation between SLC2A1 and immunostimulants across most cancer types, with CD276 and PVR predominantly implicated in LUAD." (PMID 40824962, 2025). "Owing to its close association with the biological attributes of tumors, CD276 shows promise as an emergent biomarker target for cancer diagnostics, increasingly capturing the attention of the medical community." (PMID 39319055, 2024). "It is noteworthy that a strong correlation (P<0.05) between CDCA5 and checkpoint gene expression was observed, which was found to be associated with immune gene CD276 in various types of cancer." (PMID 38213717, 2024). "B7-H3 (CD276) is an immune checkpoint molecule involved in T cell suppression, which is associated with poor survival in cancer patients." (PMID 38612786, 2024). "Among them, we focused on CD276, since the CD276-encoded protein, B7–H3, is overexpressed in several other cancers, is an immunoregulatory protein, and is already targeted by CAR-T cells." (PMID 39093440, 2024). "Immune checkpoint analysis revealed that basically all the checkpoints were upregulated in the low-risk group except for CD44, TNFSF4/9, and CD276 (marker of cancer stem cell)." (PMID 38341588, 2024). "In most tumors, high expression of CD276 is strongly associated with cancer progression and poor prognosis for cancer patients." (PMID 39076970, 2024). "The molecular signaling related to CD276 in cancer immune response is not fully understood, especially the downstream functional alteration and associated pathways upon CD276 inhibition." (PMID 38561369, 2024). "Since immune infiltrating cells are closely associated with the occurrence and development of cancer, three immune cell infiltration analysis methods were used to investigate the correlation between CD276 expression and immune cell infiltration." (PMID 36717836, 2023). "We demonstrate that the co-expression of CD147 and CD276 in BC CSCs is associated with cancer stemness and drug resistance, in addition to its known immunological function." (PMID 37648771, 2023). "CD276 is aberrantly overexpressed in numerous cancer types and is associated with poor clinical prognosis." (PMID 37648771, 2023). "The results revealed that CD276 was highly expressed, and was often associated with poorer survival and prognosis, in the majority of different types of cancer." (PMID 36717836, 2023). "Since immune checkpoint genes provide important targets for cancer immunotherapy, the associations among immune-activating genes, immune checkpoint genes, chemokine genes and chemokine receptor genes and CD276 expression were subsequently analyzed." (PMID 36717836, 2023). "The B7-H3 subvariant protein (or CD276) was overexpressed in different types of human cancer cells and was associated with disease deterioration." (PMID 36829496, 2023). "CD276 (B7-H3) is another molecule over-expressed in multiple cancer types and is implicated in evading immune surveillance." (PMID 36358665, 2022). "JMJD8 was highly associated with immune checkpoint CD276 and was an M2 macrophage biomarker in many cancers." (PMID 35898493, 2022). "Analysis of TLE3 correlation with checkpoint gene expression in pan cancers showed that Tle3 was closely linked to CD276." (PMID 36451774, 2022). "The correlation analysis of 46 immune-stimulating genes demonstrated that SERPINH1 expression was highly associated with CD276 in most cancers." (PMID 36105106, 2022). "CD276 is aberrantly overexpressed in many types of cancer, and such upregulation is generally associated with a poor clinical prognosis." (PMID 35154142, 2022). "CD276 is known to cause immune suppression by inhibiting T cell function and is currently being targeted as a check point blockade therapy for cancer; however, its specific role in MSC-mediated immunomodulation is not yet confirmed." (PMID 34736534, 2021).